ZNF331 (zinc finger protein 331)
Description:
May be involved in transcriptional regulation. May play a role in spermatogenesis.
Synonyms: RITA; ZNF361; ZNF463
Tractability: PROTAC: UniProt records ubiquitination sites on it; ubiquitination databases record sites on it.
Gene: Protein-coding gene on chromosome 19 (53,519,527 to 53,580,271, forward strand). Ensembl gene ENSG00000130844.
Subcellular location: Nucleus
Subcellular location (Human Protein Atlas): Nucleoplasm
Pathways (Reactome):
Gene expression (Transcription): Generic Transcription Pathway; Regulation of endogenous retroelements by KRAB-ZFP proteins
Gene Ontology:
Molecular function: protein binding; DNA-binding transcription factor activity, RNA polymerase II-specific; RNA polymerase II cis-regulatory region sequence-specific DNA binding; zinc ion binding
Biological process: regulation of DNA-templated transcription; regulation of transcription by RNA polymerase II
Cellular component: nucleus
Genetic constraint (gnomAD): Loss-of-function variants: 2 observed, 5.85 expected, observed/expected ratio (o/e) 0.34, 90% interval 0.14 to 1.07. That is too few expected variants to judge how well the gene tolerates losing a copy. Missense variants: 431 observed, 618.27 expected, observed/expected ratio (o/e) 0.7, 90% interval 0.64 to 0.75. Synonymous variants: 196 observed, 215.28 expected, observed/expected ratio (o/e) 0.91, 90% interval 0.81 to 1.02.
Homologues: Orthologues: chimpanzee ZNF331 (99% identical), macaque ZNF331 (99% identical), dog ZNF331 (88% identical), pig ZNF331 (87% identical), rabbit ZNF331 (78% identical). Paralogues in human: ZNF283 (66% identical), ZNF546 (53% identical), ZNF540 (53% identical), ZNF30 (53% identical), ZNF724 (52% identical), ZNF595 (51% identical), ZNF571 (51% identical), ZNF708 (51% identical), ZNF568 (51% identical), ZNF790 (51% identical), ZFP28 (51% identical), ZNF250 (51% identical), and 164 more.
Diseases named in the same sentence as ZNF331 in open-access papers:
ZNF331 is named in the same sentence as 30 diseases in open-access papers, as found by Europe PMC text mining. Sharing a sentence is not in itself a finding about the gene and the disease. The quoted sentences say what the papers report.
colorectal cancer (10 papers, 2017 to 2024). A primary or metastatic malignant neoplasm that affects the colon or rectum. "Prior studies demonstrated that ZNF331 promoter hypermethylation and its associated loss of expression is both a highly sensitive and specific marker of colorectal cancers." (PMID 38716804, 2024). "ZNF331, a gene encoding a Kruppel‐associated box zinc‐finger protein, was associated with poor prognosis in oesophageal, gastric, and colorectal cancers due to gene methylation; however, its specific mechanism remains unclear." (PMID 39098992, 2024). "Additionally, methylation of the ZNF331 promoter was associated with weaker overall survival of colorectal cancer patients." (PMID 37492743, 2023). "It has been reported that colorectal cancer patients with ZNF331 methylation have poor overall survival, and WIF1 methylation is negatively correlated with prognosis in oesophageal cancer." (PMID 33992091, 2021). "ZNF331, as a tumor suppressor gene, has also been reported to have low expression in colorectal cancer, esophageal cancer, gastric cancer, and liver cancer, and its low expression is related to hypermethylation of its promoter region." (PMID 32874785, 2020). "Most importantly, we reported high sensitivity (71%) and specificity (98%) for ZNF331 methylation in colorectal cancer early 2015, strengthening the potential of ZNF331 as a biomarker for colorectal cancer detection." (PMID 29854011, 2018). "We have previously shown that aberrant promoter methylation of ZNF331 is a potential biomarker for colorectal cancer detection with high sensitivity (71%) and specificity (98%)." (PMID 29854011, 2018). "The same study also suggested aberrant promoter methylation of ZNF331 as an independent prognostic marker for colorectal cancer, analyzing 146 samples." (PMID 29854011, 2018). "Aberrant promoter methylation was found in 71% of the samples, thus repeatedly suggesting the biomarker potential of ZNF331 for detection of colorectal cancer." (PMID 29854011, 2018). "ZNF331 is frequently methylated in human colorectal cancer, and the expression of ZNF331 is regulated by promoter region methylation." (PMID 29075358, 2017). "The function and methylation status of ZNF331 remain to be elucidated in human colorectal cancer (CRC)." (PMID 29075358, 2017). "ZNF331 suppressed colony formation, cell proliferation, and induced G1/S arrest in colorectal cancer cells." (PMID 29075358, 2017). "In this study, we found that ZNF331 is frequently methylated in human colorectal cancer and the expression of ZNF331 is regulated by promoter region methylation." (PMID 29075358, 2017). "Also, in mouse xenografts from colorectal cancer cells, high expression of ZNF331, compared to gene silencing, resulted in a smaller tumor volume." (PMID 37492743, 2023). "Moreover, the methylation status of ZNF331 is an independent prognostic marker of colorectal cancer." (PMID 34638319, 2021). "Furthermore, multivariate Cox’s analysis indicated a trend towards inferior overall survival for colorectal cancer patients with aberrant methylation of ZNF331." (PMID 29854011, 2018). "Interestingly, these findings were recently confirmed, further supporting the biomarker potential of ZNF331 in colorectal cancer." (PMID 29854011, 2018). "Methylation of ZNF331 is a poor prognostic marker in human colorectal cancer." (PMID 29075358, 2017). "ZNF331 was methylated in 67.1% (98/146) of human primary colorectal cancer samples." (PMID 29075358, 2017). "Methylation of ZNF331 is a potential colorectal cancer detection marker." (PMID 29075358, 2017). "ZNF331 suppressed human colorectal cancer cell tumor growth in xenograft mice." (PMID 29075358, 2017). "In addition, several other studies in tissue samples supported that ZNF331 methylation could function as a potential biomarker in gastrointestinal malignancies, particularly for colorectal cancer detection and prognosis prediction." (PMID 33992091, 2021).
colorectal cancer (continued). "ZNF331 may serve as a tumor suppressor in human colorectal cancer." (PMID 29075358, 2017). "Vedeld HM, Andresen K, Eilertsen IA, Nesbakken A, Seruca R, Gladhaug IP, Thiis-Evensen E, Rognum TO, Boberg KM, Lind GE: The novel colorectal cancer biomarkers CDO1, ZSCAN18 and ZNF331 are frequently methylated across gastrointestinal cancers." (PMID 29569636, 2018).
gastric cancer (9 papers, 2017 to 2023). A primary or metastatic malignant neoplasm involving the stomach. "In contrast, a recent study demonstrated that high ZNF331 methylation in peripheral blood leukocytes significantly decreased the risk of gastric cancer 40, showing that ZNF331 is also involved in regulation of the immune system." (PMID 37649596, 2023). "ZNF331 has been considered a transcriptional repressor, which functions as a tumor suppressor to suppress the growth and invasion of gastric cancer." (PMID 28490361, 2017). "Methylation of the promoter region of ZNF331 has been found frequently in human esophageal and gastric cancers." (PMID 29075358, 2017). "ZNF331 exhibits both tumor-suppressive (in gastric cancer) and tumor-promoting activities (in colon cancer cells); however, its role in kidney cancer remains unknown." (PMID 34638319, 2021). "However, ten downstream targets of ZNF331 were identified in gastric cancer based on the comparative 2D gel assay followed by mass spectrometry." (PMID 33672287, 2021). "ZNF331 was previously reported to suppress esophageal and gastric cancer growth." (PMID 29075358, 2017). "Immunohistochemical analysis in gastric cancer tissues revealed that ZNF331 has mainly cytoplasmic localization in tumors, while in normal cells, it resides within the nucleus." (PMID 33672287, 2021).
breast carcinoma (4 papers, 2012 to 2025). "Somatic mutations in USP6 (p.V678A and p.R475Q) and in ZNF331 (p.G193E) have been reported in 1% of primary breast cancer and 2% of ovarian cancer, respectively." (PMID 23107584, 2012). "Also, a recent study showed suggestive associations between DAE associated variants located in breast cancer susceptibility chromosomal regions, and prognosis (ZNF331 and CHRAC1)." (PMID 27792995, 2016). "A previous study has shown ZNF331 to display large amounts of ASE in breast cancer, citing genomic imprinting as a possible explanation." (PMID 32064050, 2020). "Using PCR and Sanger sequencing, we successfully validated the DASE predictions in this breast cancer-related network, which includes cancer causative genes ZNF331 and USP6, and breast cancer risk associated gene DMBT1." (PMID 23107584, 2012). "One study reported ZNF331 expression in T cell clusters in breast cancer with resident effector memory phenotype co-expressing regulatory elements that may involve in cell cycle regulation and upregulating GZMK over GZMB and PRF1, aligning with our observations." (PMID 40028342, 2025).
colon cancer (2 papers, 2021 to 2024). "The interaction between ZNF331 promoter methylation status and specific prognostic molecular markers of colon cancer was also evaluated." (PMID 38716804, 2024). "We thus sought to determine the potential of ZNF331 promoter hypermethylation (mZNF331) as a prognostic and predictive marker in colon cancer." (PMID 38716804, 2024). "We therefore conducted this analysis to evaluate the utility of ZNF331 promoter hypermethylation as a prognostic and/or predictive marker in stage III colon cancer patients enrolled in a large, well-annotated randomized phase III clinical trial." (PMID 38716804, 2024). "While ZNF331 promoter hypermethylation is frequently observed in CRC, our current study of a small subset of patients with stage III colon cancer suggests limited applicability as a prognostic marker." (PMID 38716804, 2024). "Other common histopathologic features (including extramural vascular, perineural and lymphovascular invasion and histologic grade) were similar between colon cancers with and without ZNF331 promoter hypermethylation." (PMID 38716804, 2024).
glioma (2 papers, 2021 to 2022). A benign or malignant brain and spinal cord tumor that arises from glial cells (astrocytes, oligodendrocytes, ependymal cells). "Hence, STAU1 depletion increased stability and half-life of ZNF331 mRNAs and inhibited glioma progression." (PMID 34633481, 2021). "In addition, in the regulation of glioma formation, the PABPC5/HCG15/ZNF331 feedback loop involving HCG15 exerted a significant function, giving a novel target for glioma therapy." (PMID 36189204, 2022).
thyroid tumor (2 papers, 2017 to 2018). A benign or malignant neoplasm affecting the thyroid gland. "Zinc finger protein 331 (ZNF331) was first identified from thyroid tumors." (PMID 29075358, 2017).
cervical tumors (1 paper, 2021).
colon adenocarcinoma (1 paper, 2024). "In this exploratory analysis of patients with stage III, resected colon adenocarcinoma treated in a prospective, randomized trial evaluating adjuvant FU/LV versus IFL (CALGB/Alliance 89,803), we evaluated the utility of ZNF331 promoter methylation as a prognostic and predictive biomarker." (PMID 38716804, 2024).
esophageal squamous cell carcinoma (1 paper, 2017). Esophageal squamous cell carcinoma (ESCC) is a type of esophageal carcinoma (EC) that can affect any part of the esophagus, but is usually located in the upper or middle third. "In our previous study, we found that the ZNF331 gene is frequently methylated in human esophageal squamous cell cancer (ESCC) and it serves as a tumor suppressor in ESCC." (PMID 29075358, 2017).
follicular thyroid adenoma (1 paper, 2005). A benign, encapsulated tumor, arising from the follicular cells of the thyroid gland. "The ZNF331 gene lies close to a frequent breakpoint region of follicular thyroid adenomas, but the question of why benzene should so markedly affect ZNF331 expression remains unclear at present." (PMID 15929907, 2005).
gastric tumour (1 paper, 2021). "In short, the methylation of ZNF331 and WIF1 we observed was limited to PBLs, which may not be extended to gastric tumour tissues." (PMID 33992091, 2021).
growth disorders (1 paper, 2019). "ZNF331 is worth considering as a candidate gene for growth disorders, though further studies are needed to elucidate the pathomechanism." (PMID 31749829, 2019).
hepatocellular carcinoma (1 paper, 2021). A malignant tumor that arises from hepatocytes. "The level of ZNF331 (with a panel of 14 other transcription factors) was recently identified with powerful predictive performance for the overall survival of hepatocellular carcinoma patients." (PMID 34638319, 2021).
Huntington disease (1 paper, 2024). Huntington disease (HD) is a rare neurodegenerative disorder of the central nervous system characterized by unwanted choreatic movements, behavioral and psychiatric disturbances and dementia. "Parkinson's and Huntington's disease were both enriched by APOC1, NUSAP1, NR4A2, ADRB2 and ZNF331." (PMID 39098992, 2024).
leukoplakia (1 paper, 2023). A white patch or plaque on a mucous membrane that cannot be characterized clinically or pathologically as any other disease. "We found 4 genes (LY75, ZNF83, ZNF160, ZNF331) common in leukoplakia and OSCC, while 9 genes appeared only in OSCC, suggesting their role in disease advancement." (PMID 37245006, 2023).
multiple sclerosis (1 paper, 2019). A progressive autoimmune disorder affecting the central nervous system resulting in demyelination. "Importantly, altered allelic expression of two imprinted genes (ZNF331 and GNAS) and five non-imprinted genes (ABLIM1, UBE2I, KIAA1267, CD6, and ATHL1) were detected between the multiple sclerosis discordant co-twins." (PMID 31850058, 2019).
Obesity (1 paper, 2023). Accumulation of substantial excess body fat. "Of note, methylome and transcriptome changes in the ZNF331 and FGFRL1 genes in leukocytes underlined the effects of a very-low-calorie ketogenic diet (600–800 kcal/d) on obesity indices." (PMID 37836535, 2023).
thyroid (1 paper, 2020). "ZNF331 is located on chromosome 19q13, a recently cloned gene encoding a zinc-finger protein involved in thyroid tumorigenesis." (PMID 32874785, 2020).
tumor (20 papers, 2014 to 2025). "Evaluating molecular features, ZNF331 promoter hypermethylation was most significantly associated with CIMP+ status (30.8% of methylated tumours, compared to 2.6% of unmethylated tumours, p < 0.0001)." (PMID 38716804, 2024). "In this study, blood-derived DNA methylation levels of two tumour-related genes, namely, ZNF331 and WIF1, and their impacts on the risk and prognosis of GC were evaluated." (PMID 33992091, 2021). "ZNF331, encoding a zinc finger protein that acts as a tumor suppressor and negative regulator of cellular growth, was found to be differentially expressed between normal and IUGR placentas." (PMID 31749829, 2019). "Methylation of ZNF331 was significantly associated with tumor size, overall survival (OS), and disease-free survival (DFS) (p < 0.01, p < 0.01, p < 0.05)." (PMID 29075358, 2017). "By whole-genome exome sequencing, 20 of non-synonymous or frameshift gene mutations were detected in sunitinib-naïve, primary tumor; all but one (ZNF331 frameshift deletion) were present also in sunitinib-resistant, metastatic lesion." (PMID 26474454, 2015). "Here, we demonstrate that the overexpression of ZNF250, ZNF324B, and ZNF331 is significantly negatively associated with tumor dedifferentiation status and that higher-grade tumors (with cancer stemness characteristics) express substantially lower levels of those transcription factors." (PMID 34638319, 2021). "One mutation, namely a frameshift deletion in ZNF331 was detected only in the primary tumor." (PMID 26474454, 2015). "One mutation, ZNF331 frameshift deletion, was detected only in the primary tumor." (PMID 26474454, 2015). "ZNF331 acts as a tumor suppressor in CRC cells, inhibiting the proliferation of CRC cells and the growth of CRC cells in xenograft mice, indicating that ZNF331 is a potential tumor suppressor for CRC." (PMID 40085529, 2025). "While they did not observe a statistically significant reduction in OS by Kaplan-Meier analysis, there was a numerical trend towards reduced survival in patients whose tumours demonstrated ZNF331 methylation." (PMID 38716804, 2024). "Kaplan-Meier analysis revealed significantly reduced 5-year DFS (p = 0.024) and overall survival (p = 0.001) in patients whose tumours demonstrated ZNF331 methylation compared to those with unmethylated tumours." (PMID 38716804, 2024). "Of the 1264 enrolled patients, 394 case subjects had sufficient tumour tissue for evaluation of ZNF331 promoter methylation status." (PMID 38716804, 2024). "As a tumor suppressor, ZNF331 inhibits GC progression by downregulating genes that promote cell growth, such as DDX5, DSTN, EIF5A, GARS, UQCRFS1, STAM and SET." (PMID 37174714, 2023). "In ZNF331, significant downregulation was found in biallelically expressing tumour samples compared to monoallelically expressing control samples, but also when compared to monoallelically expressing tumour samples." (PMID 30297886, 2018). "The tumor volumes were 289.03 ± 52.22 mm3 in ZNF331 unexpressed DLD1 cell xenografts and 180.6 ± 50.28 mm3 in ZNF331 re-expressed DLD1 cell xenografts." (PMID 29075358, 2017). "The tumor weights were 0.14 ± 0.03 g vs 0.09 ± 0.02 g in ZNF331 unexpressed and re-expressed DLD1 cell xenografts." (PMID 29075358, 2017). "The tumor volumes were smaller in ZNF331 re-expressed DLD1 cell xenograft mice compared to ZNF331 unexpressed DLD1 cell xenograft mice (p < 0.05)." (PMID 29075358, 2017). "Several ZFPs, such as ZNF217 and ZNF639, are oncogenic proteins, whereas other ZFPs, such as ZAC, ST18, ZNF382 and ZNF331, are tumour suppressors." (PMID 25714013, 2015). "In human cancers, some ZFPs, including ZAC, ST18, ZNF382 and ZNF331, function as tumour suppressors and are frequently inactivated by CpG methylation." (PMID 25714013, 2015). "In GC, ZNF331 can also curb tumor cell invasion by downregulating DSTN and ACTR3." (PMID 37174714, 2023).